ZBED9-AS1 (ZBED9 antisense RNA 1)
Gene: Long non-coding RNA gene on chromosome 6 (28,587,378 to 28,591,747, forward strand). Ensembl gene ENSG00000246350.
Gene Ontology:
Molecular function: triplet codon-amino acid adaptor activity
Biological process: translation